IL1B (interleukin 1 beta)
Diseases named in the same sentence as IL1B in open-access papers (continued):
Sharing a sentence is not in itself a finding about the gene and the disease.
cancer (continued). "In this review, we summarize these contradictory roles of NLRP3 inflammasome in cancer, shed the light on oncogenic signaling leading to NLRP3 activation and IL-1β production and outline the current knowledge on therapeutic approaches." (PMID 32733479, 2020). "ESM1 is known to be upregulated by inflammatory cytokines (IL-1β, TNF-α, and IFN-γ) and proangiogenic factors (VEGF-A and VEGF-C) and PI3K dependent pathway in cancer cell or endothelial cell." (PMID 32466580, 2020). "The results indicated that berberine determined the decrease of cancer cell viability and proinflammatory cytokine production and downregulation of P2X purinoceptor 7 (P2X7) expression, procaspase-1, and IL-1β." (PMID 33015196, 2020). "In cancer cells, TAT-FADD suppresses the canonical NLRP3 inflammasome priming and restricts the processing and secretion of proinflammatory IL-1β." (PMID 32961826, 2020). "We observed higher levels of Il-1β, Ccl2, Ccl3, Il23, and iNos mRNA in the differentiated MPRO cells cultured in the supernatant of cancer cells compared with MPRO cells cultured in SF media." (PMID 33049964, 2020). "Similar results were observed in a model of colorectal cancer, where TAMs surrounding the cancer have strong NLRP3 and IL-1β expression, as well as inflammasome activation." (PMID 32883606, 2020). "Several proinflammatory cytokines, such as IL-6, IL-1β, TNF-α, facilitate the cancer progression by recruiting and activating MDSCs at the sites of the next metastases." (PMID 33123472, 2020). "Our results, along with the findings of other authors, indicate the ability of the CV extract to induce the production of many cytokines, including IL-1β, IL-2, IL-6, IL-10, TNF-α, and IFN-γ, by immune cells and cancer cells." (PMID 33260615, 2020). "Inside carcinoma cells, Gal-9 up-regulates the expression of a variety of pro-inflammatory cytokines which are critical for MDSC differentiation, including IL-1β and IL-6." (PMID 32632113, 2020). "IL1β increases the phosphorylation of focal adhesion kinases and expression of MMP9 which are related to the adhesion and migration of cancer cells." (PMID 31398937, 2019). "CCL8 treatment of both cancer cell lines significantly upregulated the expression of CSF1 mRNA and protein (Log2FC > 1, p < 0.05), as well as TNF-α and IL-1β." (PMID 30930117, 2019). "Cancer cells can activate the hemostatic system through the expression of pro-coagulant factors including tissue factor and cancer pro-coagulant, release of inflammatory cytokines (i.e., TNF-α, IL-1β) and microparticles, and adhesion to host vascular cells." (PMID 31157239, 2019). "In tongue squamous cell carcinomas, IL-1β upregulates CXC chemokine receptor 4 (CXCR4), leading to cancer growth and metastasis." (PMID 30917608, 2019). "It ameliorates cancer in colon tissue by inhibiting the expression of VEGF, VEGFR2, HIF-1α/b, FGF, IL-1β, -6, -8, COX-2, and iNOS." (PMID 30871059, 2019). "Our previous results showed that cloned 6D cells acquired resistance to doxorubicin and tamoxifen, together with other features of aggressive cancer cells, through an EMT program induced by activation of the IL-1β/IL-1RI/β-catenin pathway." (PMID 30641908, 2019). "As a result, production of inflammatory mediators (such as IL-6, IL-1β, and TNF-α) was enhanced, supporting inflammation and cancer progression via Notch pathway activation." (PMID 30917608, 2019). "Although most of the published studies consider that M2 macrophages produce high amounts of IL-10, IL-1β, VEGF and MMP, additional subsets have been described with different proportions of cytokines related to cancer microenvironment." (PMID 31921634, 2019). "G-CSF, IL-1b, and CXCL10 are released from the metastasis-derived myeloid cells and all also trigger the NFκB pathway, which plays an important role in the cancer cell response to inflammation." (PMID 31064120, 2019).
cancer (continued). "BMA secrete various adipocytokines such as leptin, adiponectin, IL-1β, IL-6, vascular cell adhesion molecule 1 (VCAM-1), TNF-α, and VEGF, which influence cancer cell biology." (PMID 31334678, 2019). "Mechanistically, we demonstrate that bone marrow-derived IL1β promotes metastatic colony formation through activation of intracellular NFKB/CREB signalling and Wnt ligand production by cancer cells." (PMID 31676788, 2019). "During cancer, the ROS and other stress conditions such as COX-2, PGE2, pro-inflammatory cytokines like TNF-α, IL-1β, IL-6, and another NF-kB modulator take part in facilitating the activation of nuclear translocation of NF-kB via numerous mechanisms." (PMID 31556759, 2019). "IL-1β and TNFα induced IL-18 release upregulating the expression of VCAM-1 on hepatic sinusoidal endothelium (HSE) and thereby promoting cancer cell adhesion and liver metastases." (PMID 30042333, 2018). "Several studies demonstrated that ATP was released from dying cancer cells and activated dendritic cells via P2X7 signaling, which then triggered NLRP3 inflammasome activation resulting in the secretion of IL-1β." (PMID 29780380, 2018). "In our study, the cancer cells provoked M2 phenotype as demonstrated by an increase of CD163 and Arg1 and a decrease of IL-1b and IL-6 expression." (PMID 30180849, 2018). "The relevance of the interplay between Notch and IL-1β is strengthened by the evidence that effective IL-1β and CCL2 antagonists are currently in clinical review to treat benign inflammatory disease, and their transition to the cancer clinic has been proposed." (PMID 30154786, 2018). "Different from the observation that IL-1β is secreted dominantly from cancer cells in TME, in our current study, inflammatory UC-MSCs are the major source of IL-1β in the coculturing system." (PMID 29670904, 2018). "Several lines of evidence have demonstrated that key molecules that are involved in cancer-related inflammation include NF-kB, STAT3, and major inflammatory cytokines, such as IL-1b, IL-6, IL-23, and TNF-a." (PMID 29232409, 2017). "Therefore we quantified the amount of some pro-inflammatory cytokines (IL1β, TNFα, IL12-p70, IL6, IL8, IL10) by CBA and found that the SCM was highly enriched in IL6 and IL8, two pleiotropic pro-inflammatory cytokines that have been implicated in cancer progression." (PMID 28472950, 2017). "Together, these results reveal that IL1α, IL1β and GCLM are critical downstream mediators of H3 ubiquitination signalling in cancer regulation." (PMID 28300060, 2017). "Potent αDC1s, induced by cytokine cocktails containing IL-1β, TNF-α, INF-α, IFN-γ, and poly I:C, generate strong functional cytotoxic T lymphocytes (CTLs) in several type of cancers and are, on average, 20-fold more active than conventional DCs." (PMID 28088784, 2017). "TAMs accordingly produce multiple growth factors (HGF, EGF, TGF, PDGF, etc.)and inflammatory cytokines (IL‐1β, IL‐6, and TNF‐α) that each can induce EMT in cancer cells." (PMID 28599100, 2017). "Since pro-inflammatory cytokines play a critical role in the onset of cancer cachexia, we measured mRNA levels of IL6, TNFα, IL1β, and PTHrP32,33 in C26 tumors isolated from mice treated with vehicle, (−)-JQ1 and (+)-JQ1 (20 and 50 mg/kg/day)." (PMID 29167426, 2017). "Of the genes that overlapped between the P63-containing FAIRE peaks and P63 knockdown in carcinoma-derived cell lines, F3, HBEGF, IGFBP3 and IL1B were further investigated by RT-qPCR in P63 siRNA-treated NHU cells." (PMID 28282036, 2017). "Proinflammatory cytokines interleukin 1 beta (IL-1β), interleukin 6 (IL-6) and tumor necrosis factor alpha (TNF-α) regulates inflammatory response and play significant role in the development of cancer." (PMID 27034760, 2016). "We focused on IL-1β, IL-6, and TGF-β1 because these are well-known cancer progression-related factors for many malignancy types, including bladder cancer." (PMID 27698389, 2016).
cancer (continued). "In our mouse model of TNBC, radiation stimulates the cancer cell migration and development of metastasis which seems to involve multiple inflammatory pathways including those of COX-2, IL-1β and IL-6." (PMID 27282478, 2016). "Among them there were genes codifying monocyte/macrophage-derived cytokines (IL1β), and matrix related proteins such as Heparanase (HPSE) that have been widely demonstrated to increase microvessel density and reduce survival of cancer patients." (PMID 27281335, 2016). "Overall these results agree with a CagA and IL-1β-induced onset of EMT, with CagA promoting more aggressive cancer features." (PMID 27525003, 2016). "NF-κB is activated by IL-1β and TNF-α, which are downstream effectors of TLR activation that also increase stemness in cancer cells." (PMID 28116318, 2016). "Positive correlations (|r|>0.45) among CRP, IL-6, TNF-α, IL-1β, MMP-9, VEGF, and TF antigen were found in both groups of cancer patients, whereas the fibrinogen correlated only in DVT+ group." (PMID 26192925, 2015). "IL-1β up-regulated the expression of CXCR4, a CXC chemokine receptor that mediates cancer growth and metastasis, at both mRNA and protein levels in Tca8113 TSCC cells." (PMID 26176534, 2015). "In addition, since IL-1β plays an important role in cancer development, it is also interesting to know whether or not DJ-1 deficiency can impact on cancer development through regulating IL-1β levels." (PMID 25706411, 2015). "Again in the second experiment, human biofield treatment (TT2) significantly decreased IL-1β, IL-1α, MIP-2, and MIG from high levels with cancer to control/PBS levels." (PMID 26113869, 2015). "IL-1β, IL-1α, MIP-2, and MIG were upregulated by cancer and downregulated to control levels (PBS-treated mice) by TT." (PMID 26113869, 2015). "Of 11 markers previously affected, 7 markers significantly changed in the same manner: IL-1β, IL-1α, IFN-γ, MIP-2, IL-2, MIG, and IP-10, with cancer (CA2)." (PMID 26113869, 2015). "IL-1β induces the up-regulation of CXCR4 in the tongue carcinoma cell line Tca8113, suggesting that CXCR4 is a link between inflammation and cancer." (PMID 26176534, 2015). "Higher mean levels of IL-6, TNF-α, IL-1β, VEGF, MMP-9 and TF were secreted from healthy monocytes treated with the sera derived from cancer patients DVT compared to those from DVT- (p<0.01)." (PMID 26192925, 2015). "TT produced significant effects in IL-1α, IL-1β, MIP-2, and MIG, which were upregulated with cancer and brought down to control (PBS) levels." (PMID 26113869, 2015). "Being a crucial member at the crossroad between inflammation and cancer, SAG appears to be an important modulator of proinflammatory/protumorigenic molecules (IL-1β, IL-6 and TNF)." (PMID 27551463, 2015). "IL-1β and TNF-α are the most important inflammatory molecules involved in cancer-related inflammation." (PMID 26517517, 2015). "A growing body of studies suggests that NF-kB activation mediates up-regulation of inflammatory cytokines, angiogenic factors (e.g. CRP, IL-6, TNF-α, IL-1β, VEGF, MMP-9) in cancer." (PMID 26192925, 2015). "Consistent with previous reports, significant upregulations of IL-1β, IL-6, and TNF-α mRNAs in the cancer group compared to the naive group were observed." (PMID 26649065, 2015). "As expected, strong correlations between levels of IL-6, TNF-α, IL-1β, VEGF, MMP-9 and TF in plasma from cancer patients DVT+ and DVT- and those released from monocytes of the same patients were observed." (PMID 26192925, 2015). "Coincidently, we found that protumorigenic/proinflammatory cytokines, IL-1β, IL-6 and TNF, along with SAG, were significantly upregulated in the primary carcinoma tissues (P<0.01)." (PMID 27551463, 2015). "In particular, IR induces the secretion of the pro-inflammatory cytokines IL-1β and TNF-α in both animal cancer models and cancer patients." (PMID 25053129, 2014).
cancer (continued). "A number of studies have suggested that IL-1β is capable of activating p38 and JNK, and p38 and JNK play important roles in cancer cell migration and invasion." (PMID 24479681, 2014). "In the whole panel of cytokines, only IL-1β, IL-2, IL-6, TNF-α, IL-8, and MCP-1 were found to be modified in cancer patients after RT." (PMID 24800238, 2014). "M1-polarized TAMs release reactive oxygen and nitrogen intermediates to kill cancer cells or release immunomodulatory factors, such as interleukin-1β (IL-1β) and IL-12, which provoke CD8+ T cells to attack cancer cells." (PMID 24324582, 2013). "Apart from IL8, the co-regulation between NF-κB and AP1, CEBPB or STAT3 for genes IL1B, ICAM1, IL6, PTGS2, and SAA1 in the TF regulatory networks is consistent with previous observation in HNSCC or other cancer cells." (PMID 24069219, 2013). "Activation of endothelial cells by IL-1β induced the expression of ECAMs namely VCAM-1, ICAM-1 and E-selectin on endothelial cell surfaces, and these proteins facilitated the binding of cancer cells." (PMID 23460862, 2013). "The transcription of several key inflammatory factors, including IL1β, IL6 and TGFβ1, was induced in the carcinomas of both mice." (PMID 23526950, 2013). "Thus, Zeb1 may play a key role in IL-1β-induced EMT in various cancer cells." (PMID 23174018, 2012). "Here we used HeLa cells, a human epithelial carcinoma cell line, to evaluate the role of inducible HSP70 in response of IL-1β stimulation." (PMID 23185533, 2012). "Additionally, cytokines such as IL-6, IL-1β, and TNF-α, play important roles in cancer initiation, growth, and metastasis development." (PMID 40699634, 2025). "Current research on pro-inflammatory cytokines explains that IL-1A, IL-1B, IL-6, TGF-β1, and IFN-γ might be key components of the PeCa TIME and are believed to play a significant role in cancer formation." (PMID 40141426, 2025). "In systemic inflammatory diseases and cancer, NLRP3 inflammasome activation drives proteolytic cleavage of pro-caspase-1, enabling maturation and secretion of IL-1β and IL-18, potent pro-inflammatory cytokines that amplify innate immunity and promote systemic inflammation." (PMID 41555998, 2025). "Several cytokines, such as TNF-α, IL-6, IL-1β and TGF-β, are involved in the EMT of cancer cells." (PMID 40707476, 2025). "IL-1β, as a marker of NLRP3 inflammasome activation, is positively correlated with MMP9 and negatively correlated with E-cadherin, suggesting that IL-1β is involved in EMT and promotes the development of cancer." (PMID 40843171, 2025). "Similarly, other cancer types have also been reported to express high levels of NLRP3 and to secrete IL-1β, which strongly correlates with disease progression." (PMID 39858071, 2025). "Unlike other types of cell death, pyroptosis in cancer cells has contradictory effects, as IL-18 and IL-1β are produced during the process of pyroptosis, inducing M2 polarization and cytotoxic T cells exhaustion." (PMID 41373022, 2025). "For instance, pancreatic cancer (PC) cells secrete PGE2 and tumor necrosis factor (TNF) to attract macrophages; once infiltrated, the macrophages provoke inflammatory reactions in neighboring cancer cells, further amplifying PGE2 and TNF production via IL-1β signaling and attracting more TAMs." (PMID 41417432, 2025). "Based on the evidence that the pro-inflammatory cytokine IL-1β promotes cancer cell aggressiveness and may favor EMT pathway activation, we conducted Western blot analysis to determine whether IL-1β stimulation modulates the fibronectin levels in TEVs." (PMID 40725070, 2025). "Form a long-term “training imprint”, significantly enhancing phagocytic ability, cytotoxicity and the secretion capacity of pro-inflammatory cytokines such as IL-1β and TNF-α; In cancer applications, TI inducers represented by BCG vaccines have performed outstandingly." (PMID 41403926, 2025).
cancer (continued). "In addition, cancer cell–derived SAA1 promotes the recruitment of MDSCs and their differentiation from GMPs via TLR2/4 signaling, while also inducing IL-1β secretion by MDSCs." (PMID 41029721, 2025). "Although not an oncoprotein itself, IL-1β promotes the release of oncogenic cytokines such as IL-6 and IL-8 from cancer cells." (PMID 41440367, 2025). "Agonists of the cytosolic double-stranded DNA-sensing stimulator of IFN gene (STING) pathway can mediate proinflammatory conversion of cancer MDSCs; however, secretion of the NLRP3 products IL-1β and IL-18 has also been observed in certain myeloid populations following STING activation." (PMID 40377974, 2025). "Similarly, secretion of another NLRP3 inflammasome-dependent cytokine, IL-1β, was notably elevated in the IHGK cells (P < 0.01) and HSC-3 cells (P < 0.001), while SCC-24 A and −24B cancer cell lines showed negligible IL-1β response (P > 0.05)." (PMID 40338411, 2025). "PA induces anti-inflammatory effects on IL-6 that may reduce the activity of pro-inflammatory cytokines IL-1B and TNF-a, positively affecting cancer-related fatigue." (PMID 39915872, 2025). "The use of CIS in cancer therapy is usually accompanied by inflammation and increased pro-inflammatory cytokines like tumor necrosis factor-alpha (TNF-α), inducible nitric oxide synthase (iNOS), interleukin-1 beta (IL-1β), and Interleukin-6 (IL-6)." (PMID 39765772, 2024). "In additional experiments, where we compared healthy mice to 4PYR-treated animals, we found that 4PYR has contributed to significantly increased expression of cytokines related to inflammation and cancer progression, such as CCL3, CXCL1, CCL5 or IL-1A and IL-1B." (PMID 39795893, 2024). "Additionally, we found that TUBA1B+ TAMs, C1QC+ TAMs and IL1B+ TAMs were predominant in early-stage tumors, whereas VCAN+ TAMs, SLC40A1+ TAMs and APOC1+ TAMs had higher proportions in patients with advanced cancer." (PMID 39232806, 2024). "SLC40A1+ TAMs exhibited high expression level of the ferroportin gene SLC40A1, which promotes the production of pro-inflammatory cytokines such as IL-6 and IL-23 while inhibiting the production of the key inflammatory regulator IL-1β in the TME, leading to the poor prognosis for cancer." (PMID 39232806, 2024). "Cancer patients treated with DOXO experienced high levels of CRP, erythrocyte sedimentation rate, IL-6, and IL-1β that may contribute to additional complications, including organ dysfunction or failure." (PMID 38818214, 2024). "IL1β has been identified as a prognostic marker in multiple types of cancers, but we found that it failed to act as such in OS patients." (PMID 39767767, 2024). "IL8, SAT, DUSP1, IL1b, HA3, S100P, and OAZ1, which are related to cancer." (PMID 38522008, 2024). "In LA3IK-treated samples, a significant downregulation was observed among genes central in cancer-related inflammation and epithelial-mesenchymal transition (EMT), exemplified by the reduced expression of IL1B, CXCL-8, matrix metalloproteinase 1 (MMP-1), and Zeb-1." (PMID 38272230, 2024). "One such cytokine is IL-1β, a ligand for the IL-1R that produces in vivo and in vitro carcinogenic changes downstream of MAPK and NF-κB that promotes immunosuppression, angiogenesis, and the invasion of cancer." (PMID 38539448, 2024). "IL-1β and TNF-α exhibit a dual effect, demonstrating protective effects during the innate immune response against pathogens and tumors and presenting harmful effects during cancer development." (PMID 38774541, 2024). "Our study found that, compared to adenomatous polyps where IL1B expression levels were unchanged, a notable increase in expression was evident in the transition phase toward carcinoma, suggesting its potential utility as a non-invasive biomarker for CRC." (PMID 38979413, 2024). "In addition, IL-1β enhanced the migration and invasion of TRAMPC2 cancer cells which implies a pro-tumorigenic role for IL-1β." (PMID 37449203, 2023).